PEX7 (peroxisomal biogenesis factor 7)
Description:
Receptor required for the peroxisomal import of proteins containing an N-terminal PTS2-type peroxisomal targeting signal. Specifically binds to cargo proteins containing a PTS2 peroxisomal targeting signal in the cytosol. Cargo protein-binding triggers interaction with PEX5 and formation of a ternary complex composed of PEX5 and PEX7 along with PTS2-containing cargo proteins, which is translocated into peroxisomes by passing through the PEX13-PEX14 docking complex.
Synonyms: PTS2R; RD; PBD9B; RCDP1
Tractability: PROTAC: ubiquitination databases record sites on it.
Gene: Protein-coding gene on chromosome 6 (136,822,548 to 136,914,598, forward strand). Ensembl gene ENSG00000112357.
Subcellular location: Cytoplasm, cytosol; Peroxisome matrix
Subcellular location (Human Protein Atlas): Nucleoplasm; Vesicles
Pathways (Reactome):
Protein localization: Peroxisomal protein import
Gene Ontology:
Molecular function: enzyme binding; peroxisome targeting sequence binding; protein binding; protein homodimerization activity
Biological process: ether lipid biosynthetic process; peroxisome organization; protein import into peroxisome matrix
Cellular component: cytosol; peroxisomal matrix; peroxisome; peroxisomal membrane
Genetic constraint (gnomAD): Loss-of-function variants: 14 observed, 23.26 expected, observed/expected ratio (o/e) 0.6, 90% interval 0.4 to 0.94. The upper end of that interval is the gene's LOEUF score, 0.94, which puts it in group 3 of 6, group 1 being the genes least tolerant of losing a copy. Missense variants: 275 observed, 250.38 expected, observed/expected ratio (o/e) 1.1, 90% interval 0.99 to 1.21. Synonymous variants: 109 observed, 99.97 expected, observed/expected ratio (o/e) 1.09, 90% interval 0.93 to 1.28.
Gene-disease validity (ClinGen):
ClinGen rates the evidence that PEX7 causes each of these diseases.
peroxisome biogenesis disorder (autosomal recessive): Definitive.
Homologues: Orthologues: chimpanzee PEX7 (99% identical), macaque PEX7 (98% identical), rabbit PEX7 (92% identical), guinea pig PEX7 (92% identical), mouse Pex7 (90% identical), rat Pex7 (89% identical), dog PEX7 (83% identical), pig PEX7 (76% identical), zebrafish pex7 (66% identical), Drosophila melanogaster Pex7 (42% identical). Paralogues in human: GEMIN5 (24% identical), RBBP7 (23% identical), RBBP4 (22% identical), GRWD1 (20% identical), WDR24 (20% identical), WDR59 (19% identical), WDR77 (19% identical), ERCC8 (15% identical), WDR73 (15% identical).
Diseases named in the same sentence as PEX7 in open-access papers:
PEX7 is named in the same sentence as 50 diseases in open-access papers, as found by Europe PMC text mining. Sharing a sentence is not in itself a finding about the gene and the disease. The quoted sentences say what the papers report.
rhizomelic chondrodysplasia punctata (16 papers, 2011 to 2025). Rhizomelic chondrodysplasia is a form chondrodysplasia punctata, a group of diseases in which the common characteristic is calcifications near joints at birth. "Rhizomelic chondrodysplasia punctata type 1 (RCDP1) is a distinct peroxisome biogenesis disorder caused by defects in PEX7 that impair the peroxisomal pathways of plasmalogen (Pls) synthesis and phytanic acid (PA) oxidation." (PMID 35898397, 2022). "Rhizomelic chondrodysplasia punctata type 1 (RCDP1) is a peroxisome biogenesis disorder caused by defects in PEX7 leading to impairment in plasmalogen (Pls) biosynthesis and phytanic acid (PA) oxidation." (PMID 35898397, 2022). "Rhizomelic chondrodysplasia punctata (RCDP) type 1 is one of the peroxisomal biogenesis disorders caused by mutations in the PEX7 gene and is inherited in an autosomal recessive manner." (PMID 25800479, 2015). "The region contains few genes, but D6S1009 is within 100 kb of the peroxisome biogenesis factor 7 (PEX7) gene, mutations in which can cause ocular phenotypes as part of the severe systemic syndromes Refsum disease and rhizomelic chondrodysplasia punctata." (PMID 21738393, 2011). "Plasmalogen deficiency in mammals is linked to a specific bone developmental problem, in man known as rhizomelic chondrodysplasia punctata (RCDP), and RCDP type I is linked to PEX7 deficiency." (PMID 24319432, 2013). "The human peroxisomal disorder Rhizomelic Chondrodysplasia Punctata (RCDP) type 1, caused by mutations in the PEX7 gene is characterized by a clinical presentation that includes congenital cataracts, proximal shortening of long bones, contractures and hypotonia." (PMID 22163031, 2011). "As the extreme C-terminus of human HMGCR does not resemble a PTS1, we expected a PTS2 and tested this hypothesis by studying primary human fibroblasts from a patient suffering from type-1 rhizomelic chondrodysplasia punctata (RCDP1), in which the PTS2 receptor PEX7 is mutated." (PMID 38397481, 2024). "These include inherited peroxisomal disorders, often caused by mutations in one of the 14 different peroxin (PEX) genes that lead to different manifestations of the Zellweger syndrome, as well as in the case of PEX7 to rhizomelic chondrodysplasia punctata (RCDP)." (PMID 35573699, 2022). "Furthermore, loss-of-function mutations in four genes (PEX7, GNPAT, AGPS, and FAR1) that mediate peroxisomal synthesis of AAG, a necessary substrate for synthesis of plasmenyl-PE and plasmenyl-PC, result in rhizomelic chondrodysplasia punctata (RCDP)." (PMID 38582453, 2024).
peroxisomal disorders (7 papers, 2015 to 2025). "Earlier data from Japan estimated that the even broader category of peroxisomal biogenesis disorders (which includes PEX7-mediated disease) occurred only once in 500,000 births." (PMID 40519747, 2025). "Of note, three of the four PEX proteins (PEX2, PEX7 and PEX13 targeted by HIV-induced miRNAs are associated with peroxisome biogenesis disorders." (PMID 28594894, 2017). "RCDP is a recessive peroxisomal disease caused by variants in five genes: AGPS, FAR1, GNPAT, PEX5, and PEX7, which encode alkylglycerone phosphate synthase, fatty alcohol reductase 1, glycerone-phosphate O-acyltransferase, and the peroxisomal biogenesis factors 5 and 7, respectively." (PMID 40394457, 2025). "The connected component of peroxisomal disorders expressed in the hypothalamus consists of PEX19, PEX10, PEX6, and PEX7." (PMID 27748412, 2016). "In cells from patients with peroxisome biogenesis disorders, peroxisomes are absent due to mutations in one or more genes that encode critical biogenesis factors including PEX2, PEX7 and PEX13." (PMID 28594894, 2017).
Refsum disease (7 papers, 2006 to 2024). Refsum disease, biochemically characterised by phytanic acid accumulation, belongs to the group of leucodystrophic diseases. "More recently, damaging variants in PEX7 (peroxin 7, PhyH protein transporter into peroxisomes) have also been associated with a minority of cases of Refsum disease." (PMID 38411969, 2024). "This is particularly apparent in cases of Adult Refsum’s disease due to PEX7 mutations, which present with substantially milder symptoms." (PMID 34229749, 2021). "• Adult Refsum disease caused by mutation in the gene encoding phytanoyl-CoA hydroxylase (PAHX or PHYH) or the gene encoding peroxin-7 (PEX7) presents with highly elevated phytanic acid, anosmia, deafness, and RP." (PMID 17032466, 2006). "In the Refsum disease, phytanic acid accumulates throughout the body as a consequence of mutations in two genes, PHYH (the gene encoding the phytanoyl-CoA hydroxylase and PEX7 (encoding the PTS2 receptor)." (PMID 27114847, 2016).
Ataxia (3 papers, 2020 to 2022). Ataxia refers to impaired coordination of voluntary muscle movement. "Mutations in the PEX7 gene result in a broad clinical spectrum of effects, including muscle weakness, and ataxia." (PMID 32466254, 2020). "PA levels could be a valuable clinical tool to manage in order to prevent the clinical manifestation of ataxia and Purkinje cell loss overtime particularly in patients with milder form of PEX7 deficiency." (PMID 35898397, 2022). "Among the genes related to cerebellar volume in the four substructure GWASs we find genes related to ataxia (PEX7, MRPS27, PTK2), neurodevelopment (YPEL3, CASP6, TRIM11, GNB5) and microcephaly (PDCD6IP, USP28)." (PMID 35546225, 2022).
male infertility (3 papers, 2013 to 2020). The inability of the male to effect fertilization of an ovum after a specified period of unprotected intercourse. "Pex7-, Gnpat-, and Agps-deficient mice all show male infertility, whereas male Tmem189-deficient mice are fertile." (PMID 32209662, 2020). "In addition, a depletion of ether lipids also causes male infertility in PEX7 and GNPAT knockout mice." (PMID 24319432, 2013).
cataract (2 papers, 2011 to 2022). Partial or complete opacity of the crystalline lens of one or both eyes that decreases visual acuity and eventually results in blindness. "The AG diet also prevented the development of cataracts in Pex7 KO pups." (PMID 22163031, 2011). "We previously reported the initial characterization of a hypomorphic Pex7 mouse model that resembled a mild RCDP1 phenotype and showed early cataracts, abnormalities of lens epithelial cells and delayed skeletal ossification." (PMID 35898397, 2022). "Whereas Pex7 KO pups fed a control diet showed bilateral cataracts as soon as the pups opened the eye lids (age P14-P15), AG-fed Pex7 KO pups failed to develop cataracts or developed a unilateral small nuclear cataract." (PMID 22163031, 2011).
Arthritis (1 paper, 2025). Inflammation of a joint. "The observed arthritis may potentially relate to PEX7 deletion, while deletions in IL20RA and IL22RA2 might exacerbate inflammatory dysregulation or skin eruption." (PMID 40859316, 2025).
cardiomyopathies (1 paper, 2024). "Mutations in AGPS, another PEX7-dependent PTS2-protein, also result in cardiomyopathies." (PMID 38365851, 2024).
dyslipidemia (1 paper, 2024). "PEX11A and PEX7 were among the most upregulated peroxisome-related proteins and are essential for proper peroxisomal function and the prevention of dyslipidemia and obesity." (PMID 39280921, 2024).
encephalitis (1 paper, 2017). An acute inflammatory process affecting the brain parenchyma. "Levels of PEX7 protein were also significantly (40%) lower in the sample from an HIV patient without encephalitis or HAND, however in three HAND samples, steady state levels of PEX7 protein were lower than those seen in HIV patients without HAND as well as non-infected patients." (PMID 28594894, 2017).
HIV-1 infection (1 paper, 2020). The type species of lentivirus and the etiologic agent of acquired immunodeficiency syndrome (AIDS). "Seventy-two hours later, the relative levels of four peroxisomal biogenesis factors (PEX2, PEX7, PEX11B, and PEX13) that are downregulated during HIV-1 infection of human cells were assessed by immunoblotting." (PMID 32127461, 2020).
infertile (1 paper, 2021). "Peroxin 7 (Pex7) knockout mice displayed severely depleted plasmalogens, while adult mutant mice were infertile and exhibited testicular atrophy." (PMID 34445473, 2021).
islet cell tumors (1 paper, 2007). "Consistent with previously published findings, genes with significantly elevated expression in islet cell tumors included insulinoma-associated 1 (INSM1), glutaminyl-peptide cyclotransferase (QPCT), fibrinogen B beta polypeptide (FGB), peroxisomal biogenesis factor 7 (PEX7)." (PMID 17389914, 2007).
lymphoid cancers (1 paper, 2023). "Four genes, INTU (p-value 0.005), ASXL1 (p-value 0.009), EHHADH (p-value 0.03) and PEX7 (p-value 0.02), were associated with lymphoid cancer after multiple testing correction for 7 genes when GnomAD exomes were used as controls." (PMID 37379307, 2023). "Stop-gain variant NM_015693.4:c.581G>A in INTU in the Hedgehog signalling pathway and stop-gain variant NM_000288.4:c.875T>A in PEX7 in peroxisomal pathway each segregated with lymphoid cancers in families, suggesting that these variants in these genes may be related to risk of lymphoid cancer." (PMID 37379307, 2023). "Three genes, INTU (p-value 0.004), PEX7 (p-value 0.02), and EHHADH (p-value 0.02) were associated with lymphoid cancers after multiple testing correction for 6 genes with ExAC controls." (PMID 37379307, 2023). "The genes EHHADH, INTU, PEX7, and ASXL1 were found to have a significantly higher burden of deleterious variants in cases than controls; variants in these genes may contribute to risk of lymphoid cancers in specific individuals." (PMID 37379307, 2023).
thyroid cancer (1 paper, 2017). "In thyroid cancers, the expression of peroxisomal-biogenesis genes PEX7, PEX11B and PEX19 was significantly increased by energy metabolism." (PMID 28582771, 2017).
infection (5 papers, 2017 to 2023). The state of being infected such as from the introduction of a foreign agent such as serum, vaccine, antigenic substance or organism. "However, infection of mice with the Sid1-depleted strain produced an equivalent fungal burden in lungs as that of Sid1-expressing yeasts at 8 days post-infection but was strongly attenuated at 14 days similar to the results with the PTS2-protein import pathway-deficient strain (PEX7-RNAi)." (PMID 37432032, 2023). "The loss of multiple PEX proteins was evident at 24-h post-infection; however, by 48-h, the reduction in PEX3, PEX7, PEX11B, PEX13 and PEX19 was much more pronounced." (PMID 31311201, 2019). "Immunoblotting revealed that infection of primary macrophages, a physiologically relevant cell type in HIV patients, resulted in dramatic loss of PEX2, PEX7, PEX13, and to a lesser extent, PEX11B." (PMID 28594894, 2017). "Depletion of Pex7 function did not cause a reduction in the lung fungal burden compared to Pex7-producing H. capsulatum yeasts 8 days post-infection of mice unlike the loss of PTS1-dependent protein import." (PMID 37432032, 2023). "Depletion or loss of the Pex5 and Pex7 cytosolic receptors for PTS1 and PTS2, respectively, attenuates H. capsulatum virulence, indicating a requirement for specific peroxisome matrix proteins at different stages of infection." (PMID 37432032, 2023). "These loci exhibited negative (ELN, SASH1, and SMAD7) and positive (CDSN, NCSTN, and PEX7) relationships between minor allele frequency and infection severity, with no overarching pattern evident in control loci lacking association with mange severity." (PMID 33664786, 2021). "Infection with an isogenic Nef knockout virus had a similar effect on PEX2, PEX7, PEX13, and PEX11B as wild-type HIV-1." (PMID 32127461, 2020). "Unlike wild-type HIV-1, infection with Vpu-S52,56D and Vpu-S52,56N viruses did not result in a significant loss of PEX2, PEX7, PEX11B, or PEX13 in HeLa-CD4/CXCR4/CCR5 cells, macrophages, or T cells." (PMID 32127461, 2020). "However, at 14 days post-infection, yeasts lacking Pex7 had lower lung fungal burdens compared to Pex7-producing yeasts." (PMID 37432032, 2023).
tumor (2 papers, 2021 to 2025). "In contrast, analysis for mRNAs encoding for peroxisomal biogenesis proteins (Pex7, Pex10, Pex12), and proteins for peroxisomal proliferation (Pex11α, Pex11β) were significantly upregulated in PMA tumor compared to control tissue." (PMID 34360635, 2021).
bacterial infection (1 paper, 2019). "Drosophila macrophage-like cell lines with no functional peroxisomes, generated by RNA interference-mediated depletion of the peroxisome biogenesis factors (peroxins) Pex5 or Pex7 (designated as PEx5-i or Pex7-i, respectively), had an impaired ROS and RNS response to bacterial infection." (PMID 31398943, 2019).
peripheral neuropathy (1 paper, 2011). A disorder affecting the peripheral nervous system. "We found that Pex7 KO mice develop a peripheral neuropathy with reduced motor nerve conductance velocity (MNCV)." (PMID 22163031, 2011).
PEX7 also shares sentences with these, for which no sentence is quoted: rhizomelic chondrodysplasia punctata type 1 (7 papers); peroxisomal biogenesis disorders (4); Zellweger spectrum disorders (3); achondroplasia (1); achromatopsia (1); alopecia (1); Anosmia (1); Breast Invasive Carcinoma (1); Burkitt lymphoma (1); cancer (1); cutis laxa (1); deafness (1); developmental delay (1); epilepsy (1); episodic ataxia (1); episodic ataxia type 1 (1); hidradenitis suppurativa (1); Huntington disease (1); Hyperkeratosis (1); hyperplasia (1); ichthyosis (1); intestinal ulcers (1); microcephaly (1); nodular sclerosis (1); Obesity (1); Palmoplantar keratoderma (1); psoriasis (1); sickle cell anemia (1); spondyloepiphyseal dysplasia congenital (1); Testicular atrophy (1).
A further 1 disease shares a sentence with PEX7 in 1 paper.